RNU6-918P (RNA, U6 small nuclear 918, pseudogene)
Gene: Small nuclear RNA gene on chromosome 9 (98,032,230 to 98,032,335, forward strand). Ensembl gene ENSG00000212521.
Homologues: Orthologues: chimpanzee U6 (99% identical), macaque U6 (95% identical), rabbit U6 (86% identical), guinea pig U6 (70% identical). Paralogues in human: RNU6-1152P (85% identical), RNU6-536P (85% identical), RNU6-1131P (84% identical), RNU6-393P (84% identical), RNU6-41P (84% identical), RNU6-460P (84% identical), RNU6-621P (84% identical), RNU6-686P (84% identical), RNU6-820P (84% identical), RNU6-1060P (83% identical), RNU6-1181P (83% identical), RNU6-15P (83% identical), and 1289 more.